ADCK5 (aarF domain containing kinase 5)
Description:
The function of this protein is not yet clear. It is not known if it has protein kinase activity and what type of substrate it would phosphorylate (Ser, Thr or Tyr).
Synonyms: FLJ35454
Tractability: Antibody: UniProt predicts a signal peptide or a membrane-spanning region; the Human Protein Atlas places it where antibodies can reach. PROTAC: a small molecule that binds it is known.
Target class: Enzyme; Transferase
Gene: Protein-coding gene on chromosome 8 (144,373,101 to 144,393,242, forward strand). Ensembl gene ENSG00000173137.
Subcellular location: Membrane
Subcellular location (Human Protein Atlas): Cytosol; Plasma membrane
Gene Ontology:
Molecular function: protein binding
Cellular component: mitochondrion; membrane
Genetic constraint (gnomAD): Loss-of-function variants: 40 observed, 52.12 expected, observed/expected ratio (o/e) 0.77, 90% interval 0.6 to 1. The synonymous counts are far from expectation, so gnomAD's model fits this gene poorly and the ratio says little. Missense variants: 744 observed, 701.91 expected, observed/expected ratio (o/e) 1.06, 90% interval 1 to 1.13. Synonymous variants: 429 observed, 300.08 expected, observed/expected ratio (o/e) 1.43, 90% interval 1.32 to 1.55.
Homologues: Orthologues: chimpanzee ADCK5 (99% identical), macaque ADCK5 (92% identical), pig ADCK5 (84% identical), mouse Adck5 (81% identical), guinea pig ADCK5 (80% identical), rat Adck5 (80% identical), dog ADCK5 (78% identical), zebrafish adck5 (60% identical), tropical clawed frog adck5 (60% identical), Drosophila melanogaster Adck5 (38% identical). Paralogues in human: ADCK1 (33% identical), COQ8A (19% identical), COQ8B (19% identical), ADCK2 (16% identical).
Diseases named in the same sentence as ADCK5 in open-access papers:
ADCK5 is named in the same sentence as 9 diseases in open-access papers, as found by Europe PMC text mining. Sharing a sentence is not in itself a finding about the gene and the disease. The quoted sentences say what the papers report.
lung carcinoma (4 papers, 2022 to 2025). "In lung cancer, ADCK5 overexpression has been associated with increased invasion and migration, suggesting a role in tumor progression and metastasis." (PMID 40565246, 2025). "It has been shown that ADCK5 regulates lung cancer cell invasion and migration." (PMID 37835536, 2023). "ADCK5 phosphorylates Sox9 and thereby regulates PTTG1 in lung cancer cells, which leads to a change in the migrative and invasive behavior of these cells." (PMID 35205819, 2022).
breast carcinoma (1 paper, 2020). "ADCK5, ETNK2, PSKH2, RPS6KC1, and SCYL3 are all significantly focally amplified in breast cancer samples as well but are not located in a peak region." (PMID 33205077, 2020).
pancreatic cancer (1 paper, 2023). "In addition, the TCGA (PAAD) and GTEx (PAAD) databases obtained via GEPIA2 showed that these genes were expressed at higher rates in the tissues of pancreatic cancer tumors than in normal tissues, with the exception of Adck5." (PMID 37835536, 2023). "Pbk, Fastk, Cdk19, Adck5, Trim28, and Pfkp are the genes that may regulate CD73 in pancreatic cancer." (PMID 37835536, 2023). "Pbk, Fastk, Cdk19, Adck5, Trim28, and Pfkp may be the regulatory genes for CD73 in pancreatic cancer." (PMID 37835536, 2023).
prostate tumor (1 paper, 2023). "Compared to the normal tissue, the levels of CENPA, ADCK5, FOXM1, TFAP4, and MAPK were up-regulated in prostate tumor tissue, with a decrease in the expression of LGALS3 and BAG3." (PMID 36891298, 2023).
uveal melanoma (1 paper, 2020). A melanoma derived from melanocytes of the uveal tract. "For example, high ADCK5 mRNA levels are a negative prognostic indicator in KIRC, liver hepatocellular carcinoma (LIHC), UCEC, and uveal melanoma (UVM)." (PMID 33205077, 2020).
cancer (2 papers, 2020 to 2025). A tumor composed of atypical neoplastic, often pleomorphic cells that invade other tissues. "Other understudied kinases that score favorably in the majority of cancer cohorts include PKMYT1 (Tchem), DCLK3 (Tchem), BRSK1 (Tchem), ADCK5 (Tdark), and LMTK3 (Tbio)." (PMID 33205077, 2020).
tumor (1 paper, 2025). "ADCK5 was found to be upregulated in prostate tumor tissues and implicated in the induction of senescence, a process that can have both tumor-suppressive and tumor-promoting effects depending on the cellular context." (PMID 40565246, 2025). "A 2023 study discovered a prognostic signature consisting of eight senescence-related genes, including ADCK5, suggesting its involvement in tumor progression and cellular senescence." (PMID 40565246, 2025). "Furthermore, ADCK5 has been implicated in the phosphorylation of SOX9 at Ser181, a modification known to be critical for tumor cell proliferation, differentiation, and survival." (PMID 40565246, 2025).
ADCK5 also shares sentences with these, for which no sentence is quoted: diabetes (1 paper); psychiatric disorder (1).